TNF (tumor necrosis factor)
Diseases named in the same sentence as TNF in open-access papers (continued):
Sharing a sentence is not in itself a finding about the gene and the disease.
aneurysm (70 papers, 2009 to 2026). Bulging or ballooning in an area of an artery secondary to arterial wall weakening. "In the analysis, patients with AAA had a high concentration of OPGN and TNF-α, which have been associated with aneurysm progression, given their role in the inflammatory process." (PMID 41496900, 2025). "Both IL-1β and TNF-α have been associated with the progressive inflammatory process that promotes aneurysm progression." (PMID 40440080, 2025). "Mice deficient in TNF-α developed smaller aneurysms than TNF-α sufficient controls in response to peri-aortic calcium chloride application." (PMID 36289670, 2022). "Additionally, TNF-a, a cytokine implicated in aneurysm pathogenesis, has been shown to be elevated in patients with PTSD and MDD." (PMID 37600234, 2023). "This may be explained by the co-localization of TNF-α to smooth muscle cells in cerebral aneurysms found in mice and ultimately the loss of smooth muscle cells in unruptured and furthermore ruptured aneurysms." (PMID 24739142, 2014). "We have previously found that TNF-α triggers apoptosis in a dose-dependent fashion in cultured cerebrovascular smooth muscle cells, and this may contribute to both aneurysm progression and rupture through loss of focal cerebrovascular contractility." (PMID 24739142, 2014). "Samples from patients with AAA have consistently shown elevation of TNF levels in both plasma and aneurysm wall tissue samples, thereby suggesting that TNF plays a significant role in the pathogenesis of the disease." (PMID 39846252, 2025). "Another molecular mechanism by which TNF-α appears to be involved in enhancing aneurysms is by promoting the expression of Kruppel-like transcription factor 4 (KLF4)." (PMID 38611112, 2024). "In turn, research published by Batra indicates that it is TNF-α that is highly responsible for the development of aneurysms." (PMID 37627563, 2023). "Another animal study revealed less common aneurysm development and rupture of developing aneurysms in TNF-α knockout mice." (PMID 37873057, 2023). "Clinical studies have indicated that elevated levels of TNF in the serum of AAA patients are significantly associated with AAA symptoms, and levels of IL-6 and IL-8 are positively correlated with aneurysm diameter." (PMID 38111889, 2023). "Correlation analysis showed that IL-37 was positively correlated with IL-6, TNF-α, age, aneurysm diameter, SBP, and DBP." (PMID 35602104, 2022). "Correlation analysis revealed that IL-37 was positively correlated with IL-6, TNF-α, age, aneurysm diameter, and blood pressure." (PMID 35602104, 2022). "IL-1, IL-6, IL-12, and TNF-α can lead to the accumulation of CD4+ T cells, whose effector cells can produce MMPs and cathepsins, causing aneurysm formation and rupture through damage to the aortic wall, inflammation, and loss of VSMCs." (PMID 36505348, 2022). "Others have previously shown that inhibition of TNF by gene deletion reduces CaCl2-induced aneurysm growth." (PMID 36186984, 2022). "A previous study has shown that TNF-α secreted by macrophages is highly expressed in ruptured human aneurysms." (PMID 33867914, 2021). "The protein expression levels of COL4A2, MYLK, and VCL were decreased after SMCs were intervened with TNF‐α, consistent with the results from mass spectrometry on aneurysm samples (E‐G)." (PMID 33389819, 2021). "The resultant aneurysm out-pouching is likely accompanied by local increase in chemokines and cytokines (IL-1β, IL-17, TNF-α) in blood of the aneurysm lumen." (PMID 34203780, 2021). "Previous research revealed an increase ininfiltrated macrophages exhibiting a robust production of cytokines, including IL-6, IL-8, TNFα, and IL-1β, and specific patterns of macrophage polarization involving in aortic inflammation and aneurysm formation." (PMID 33158139, 2020). "Results from a murine aneurysm model suggested that TNF-α promotes MMP-2 and MMP-9 expression, increasing macrophage infiltration into the aortic tissue, thereby leading to aneurysm formation." (PMID 31989839, 2020).
aneurysm (continued). "Upon treatment of AngII-induced aneurysms (TNFα and CaPO4-independent, RANKL-dependent) with RANKL-neutralizing antibody, we observed decreased TRAP and MMP-9 expression." (PMID 31546645, 2019). "Reducing TNF-α action in the IA wall carries a beneficial effect on attenuating aneurysm progression by inhibiting inflammation as well as arterial remodeling." (PMID 30808715, 2019). "In a study using pre- to post-operative arterial blood samples for 13 days in patients with ruptured aneurysms and intact aneurysms, an increase of TNFα, IL-1β, and IL-6, was found." (PMID 29483877, 2018). "Numerous studies have demonstrated that TNF-α increases and plays a critical role in the occurrence and development of aneurysms." (PMID 30555299, 2018). "In our current and earlier studies, the increase in IL-1β and TNF-α and the imbalance between MMP-9 and TIMP-2 were associated with aneurysm rupture in ovariectomized aneurysm rats." (PMID 28969701, 2017). "TNF-α which has a pivotal role in the process of inflammation is a particularly dominant cytokine secreted by inflammatory cells within aneurysms." (PMID 26918963, 2016). "The concentration and the time of TNF-α were chosen based on previous reports which suggest the culture system closely mimic chronic, long-term TNF-α-induced signaling in aneurysms." (PMID 26918963, 2016). "TNF-α mediates inflammatory response and incites MMPs release, down-regulate elastin gene expression and initiates aneurysms." (PMID 26918963, 2016). "Experimental work in animals has shown that TNF-α is released in aneurysm walls, induces inflammatory cytokine expression and macrophage infiltration, and drives both the formation and the rupture of IA." (PMID 25922566, 2015). "This is consistent with the previously demonstrated importance of IL-1β, TNF-α, and IL-6 in aneurysm pathogenesis." (PMID 25922566, 2015). "A number of single-nucleotide polymorphisms (SNPs) in the gene for TNF-α have been identified as risk factors for IA or SAH in patients, and human aneurysm specimens display increased expression of the molecule." (PMID 25922566, 2015). "TNF-α-induced macrophage infiltration and phagocytosis may also contribute to this process as the quantity of apoptotic cells has been associated with cerebral aneurysm rupture and macrophage infiltration was increased furthermore in ruptured versus unruptured aneurysms." (PMID 24739142, 2014). "TNF-α expression co-localized to both smooth muscle cells and macrophages in both unruptured (B6 to 7) and ruptured aneurysms (C6 to 7)." (PMID 24739142, 2014). "Animals began treatment with DTH 3 days prior to elastase injection and were compared to both mice receiving vehicle undergoing aneurysm induction and TNF-α knockout mice undergoing aneurysm induction." (PMID 24739142, 2014). "Consistently, the activity of TNF-alpha converting enzyme (TACE), an enzyme responsible for TNF-alpha release, was induced in the arterial walls after aneurysm induction in a rat model." (PMID 24685329, 2014). "TNF-α mRNA extracted from unruptured, and even more so in ruptured aneurysms, was significantly elevated as compared with sham mice." (PMID 24739142, 2014). "Circulating levels of TNF-α are markedly elevated during acute KD, and the degree of elevation correlates with the coronary artery damage and the development of aneurysms." (PMID 25161773, 2014). "In the wall of an AAA there is up-regulation of pro-inflammatory IL-1β, IL-6, IL-10 and TNF-α, which have been shown to positively correlate with aneurysm growth." (PMID 20964810, 2010). "The present study’s findings are notable in that CL treatment led to significant reductions not only in MMP expression but also in TNF-α and IL-6 levels, supporting its dual role in modulating both immune activation and the inflammatory cascade involved in aneurysm pathophysiology." (PMID 40868841, 2025).
aneurysm (continued). "Clearly, TNF-α seems to efficiently prevent the expression of contractile phenotype markers of VSMCs, thereby enabling phenotype transition in them and facilitating the formation of aneurysms in the cranial arteries." (PMID 38611112, 2024). "Pro-inflammatory cytokines such as resistin, leptin, and TNFα have been shown to induce changes leading to the formation of aneurysms, while adiponectin is the only known compound that is secreted by adipose tissue and limits the development of aneurysms." (PMID 35745168, 2022). "In addition, matrix metalloproteinase 9 (MMP9) is activated by TNF-α, which leads to the destruction of elastin and aneurysms formation in the blood vessel wall, and increased NO concentration, which leads to the blood vessel wall's expansion and damage." (PMID 35924269, 2022). "Similarly, transplanting RIP3(+/−) aorta into RIP3(+/+) mice caused aneurysm resistance, and the underlying mechanism was RIP3 deletion, which inhibited the necrosis of SMCs and the production of inflammatory factors TNF-α and p6525." (PMID 34290266, 2021). "Additionally, higher levels of TNF-α were shown in asymptomatic AAA patients compared to patients with either symptomatic AAA or aneurysm rupture." (PMID 34572424, 2021). "In summary, although the TNF-α level and macrophage number were similar in ScSnJ and ScNJ mice during aneurysm initiation, knockout of TLR4 signaling reduced IL-6 and MCP-1 levels, suppressed HMGB1 and RAGE expression and interfered with consequent accumulation of macrophages." (PMID 26741694, 2016). "Additionally, the incidence of aneurysm formation and rupture was significantly decreased in TNF-α knockout mice and those pre-treated with DTH." (PMID 24739142, 2014). "Alterations in TNF-α have been associated with cerebral aneurysm in humans, but a direct role in aneurysm formation or rupture has not been defined." (PMID 24739142, 2014). "Gal-1 deletion in this model led to reduced aneurysm severity and inflammation, suggesting that excessive expression may compromise vascular integrity by amplifying tumor necrosis factor-alpha (TNF-α)-driven inflammatory responses in vascular smooth muscle cells and adventitial fibroblasts." (PMID 40572708, 2025). "However, the precise role of TNF-α in aneurysm progression and rupture remains to be elucidated." (PMID 40244203, 2025). "Considering the high amount of inflammatory cells infiltrating the aneurysm wall, the first condition consisted of the interaction with activated immune cells, whereas the second one was based on the exposure to a combination of recombinant inflammatory cytokines TNF-α/IL-1β at 25 ng/ml each." (PMID 28446225, 2017). "During the first stages of aneurysm development, via their capacity to produce high amounts of TNFα, these cells could play the role of “lymphoid tissue inducer” (LTi) cells by stimulating stromal “lymphoid tissue organizer” LTo cells, thus initiating ATLO formation." (PMID 24587165, 2014). "Additionally, although DTH has been found to be a specific inhibitor of TNF-α synthesis, it may have additional properties that contribute to inhibition of aneurysm formation and rupture." (PMID 24739142, 2014). "The role of TNF-α in aneurysm progression and rupture is unknown." (PMID 24739142, 2014). "Thus, it could be expected that signaling by the main receptor of another Th1 cytokine like TNF would also be protective against aneurysms." (PMID 19582157, 2009). "Golph3l upregulation by Klf5 facilitates TNF‐α and TNFSF12 secretion from AngII‐stimulated VSMCs by inducing Golgi compaction, which is essential for AIP and aneurysm development." (PMID 41317401, 2026). "Inflammatory cytokine signaling, particularly expression of IL-Iβ, TNF-α, IL-12, and IL-23, have been shown to be important drivers of AAA progression, and inhibition of many of these cytokines can prevent aneurysm formation." (PMID 39846252, 2025).
aneurysm (continued). "Serum BDNF, TNF-α, caspase-3, AChE, and BChE levels were measured in 20 patients with spontaneous SAH due to aneurysms." (PMID 37873057, 2023). "In an animal model of KD induced by Lactobacillus casei cell wall extract, the process of coronary arteritis and aneurysms can be ablated by blocking the TNF receptor, suggesting that TNF-α can directly induce coronary artery lesions." (PMID 35052869, 2022). "Elevated TNF levels have been observed in both plasma and aneurysm wall samples from patients with AAA, suggesting that TNF plays a significant role in the pathogenesis of the disease." (PMID 36186984, 2022). "Results showed CCR7, TNF and CXCR4 related miRNA-genes network were preserved in all three kinds of aneurysms, which highlighted the common molecular networks shared by aneurysmal diseases." (PMID 34637689, 2021). "The activated ADAMs are able to directly degrade structural elements of the arterial wall and to activate other MMPs and the TNF-α/c-JNK pathway, which, as part of a vicious circuit, contribute to damaging the aneurysm." (PMID 33573220, 2021). "Osteoclast-targeted treatment of mouse CaPO4-induced aneurysms (TNFα and CaPO4-dependent, RANKL-independent) with bisphosphonate was effective in inhibiting aneurysm formation and TRAP expression." (PMID 31546645, 2019). "TNF-α knockout mice and those pre-treated with DTH had significantly decreased incidence of aneurysm formation and rupture as compared to sham mice." (PMID 24739142, 2014). "Further support demonstrates that a lack of functional TNF-α in mice attenuates CaCl2-induced aneurysm development." (PMID 39846252, 2025). "In BS, TNFα results in EC apoptosis and induces the expression of proinflammatory mediators, including metalloproteinases MMP-2 and MMP-9, which are important in ECM destruction and aneurysm formation." (PMID 36834577, 2023). "However, after 7 days of healing, all humoral inflammation markers examined (TNF-α, IL6, MMP-2, MMP-9 and FGF) were markedly increased in coiled aneurysms." (PMID 37533024, 2023). "In support of this, a lack of functional TNF in mice has been shown to attenuate CaCl2–induced aneurysm development." (PMID 36186984, 2022). "However, in a different mouse model (elastase perfusion), knockout of IL-17 and IL-23 resulted in reductions in aneurysm diameter and cytokine levels (MCP-1, RANTES, KC, TNF-α, MIP-1α, and IFN-γ)." (PMID 31989839, 2020). "TNF-α knockout mice were 12.4 times (95% CI 1.6 to 94.2, P = 0.015) and those treated with DTH were 4.1 times (95% CI 1.2 to 14.1, P = 0.028) less likely to have aneurysm rupture as compared to mice receiving vehicle." (PMID 24739142, 2014). "TNF-α expression was decreased in TNF-α knockout mice, those pre-treated with the synthesized TNF-α inhibitor DTH, and controls versus unruptured and ruptured aneurysms." (PMID 24739142, 2014). "To figure out if the sVEC levels are influenced by TNF-a and ADAM10, as suggested by the in vitro data, we performed a simple linear regression analysis including all disease categories and separately for the aortic pathologies including aortic dissection and aneurysm." (PMID 39501015, 2024). "TNF-α expression was higher in unruptured aneurysms and highest in ruptured aneurysms, but this may be due to inflammation caused by SAH rather than increased TNF-α expression leading to aneurysmal rupture." (PMID 24739142, 2014). "Additionally, TNF-α levels increased more in ruptured aneurysms than in non-ruptured ones." (PMID 37873057, 2023). "Furthermore, genes related to inflammation (TNF-α, monocyte chemoattractant protein 1) were upregulated, whereas proteinases (MMP 2 and 9) and structural proteins (collagens and fibronectin) were expressed at lower levels in FD treatment compared with coiled aneurysms." (PMID 37533024, 2023).
aneurysm (continued). "Increased expression of TNF-α in human and mouse ruptured cerebral aneurysms may be a reflection of the inflammatory response following rupture rather than a mechanism leading to aneurysm instability and rupture." (PMID 24739142, 2014). "In aneurysms, mean TNFR1 levels reduced non-significantly (p = 0.07) by 50% after TNF inhibition, but the histological location in murine AAAs was unaffected and similar to that in human AAAs." (PMID 36186984, 2022). "The animal study did not, however, show an increase of the final products TNF and GZMB in the aneurysm group." (PMID 25993291, 2015). "As compared with sham mice, TNF-α protein and mRNA expression was not significantly different in TNF-α knockout mice or those pre-treated with DTH, but was elevated in unruptured and furthermore in ruptured aneurysms." (PMID 24739142, 2014).